FGF21 (fibroblast growth factor 21)
Diseases named in the same sentence as FGF21 in open-access papers (continued):
Sharing a sentence is not in itself a finding about the gene and the disease.
Insulin resistance (continued). "In addition to the effects in insulin resistance and glucose metabolism, FGF19 increases serum BHB levels even in Fgfr4 KO mice, like FGF21." (PMID 21437243, 2011). "For example, both FGF21 and AKT1S1 (also known as PRAS40) are substrates for phosphorylation by AKT kinase, and effect fatty liver disease, while IRF3 mediates HFD-induced insulin resistance and impaired hepatic glucose metabolism trough a mechanism involving AKT." (PMID 39060446, 2024). "Knockout of the FGF21 gene in liver tissue can activate glucose-6-phosphatase and phosphoenolpyruvate carboxykinase through STAT3/SOCS3 pathway, thus increasing gluconeogenesis and glycogen decomposition, resulting in the aggravation of liver insulin resistance." (PMID 36982739, 2023). "Surprisingly, the combination of OVX and FGF21 LKO resulted in exacerbation of whole body glucose metabolic abnormalities, as reflected by more impaired glucose and pyruvate tolerance, and worsened (p = 0.09) insulin resistance in OVX female mice after FGF21 LKO." (PMID 37834368, 2023). "Because FGF21 can reduce insulin resistance, there is also an interesting study that does not focus on how FGF21 alleviates insulin signaling pathways but instead focuses upstream to modify FGF21 and construct FGF21 analogs through protein engineering to enhance its functionality and perdurability." (PMID 38069273, 2023). "Our findings did not support any relationship between miR-150 and markers of insulin resistance such as insulin, adiponectin, or FGF21, but showed that miR-150 might be an important regulator in the cholesterol and triglyceride metabolisms." (PMID 35498403, 2022). "Similarly, melatonin did not mediate HFD-induced glucose intolerance or insulin resistance in FGF21−/− mice." (PMID 36207302, 2022). "Also, a lack of difference in HOMA-IR among groups further suggests that the change in FAR is likely due to the regulatory effect of FGF21 on adiponectin and not an effect of insulin resistance on the latter." (PMID 33071964, 2020). "Similarly, we failed to reject the null hypothesis of no change from pre‐ to postintervention for fasted plasma glucose, TAG, FGF21, GLP‐1, serum insulin concentrations, homeostatic model assessment of insulin resistance, or serum osmolality (all P ≥ 0.136)." (PMID 32108442, 2020). "Moreover, subjects with T2DM were reported to have significantly higher plasma levels of FGF21 than insulin-sensitive controls, with FGF21 levels positively correlated with BMI, HOMA-IR, and Matsuda index, suggesting a strong correlation with insulin resistance." (PMID 32158768, 2020). "From these results, one could speculate that liver fat reduction may not necessarily precede the improvements in hepatic insulin resistance, given that fasting insulin, and to some extent also FGF-21, may partly reflect changes in hepatic insulin sensitivity." (PMID 31685793, 2019). "Because FGF21 is increased by KD but cannot correct insulin resistance, we hypothesized an impaired FGF21 response in target tissues." (PMID 25973847, 2015). "The lack of an elevation in FGF21 in the maternal serum of women with PE in our study may be due to differences in the characteristics of the study participants such as BMI, insulin resistance, gestation at blood sampling and parity." (PMID 25890271, 2015). "However, FGF21 administration alone at 22°C did improve insulin resistance in LmnaADKO mice, but not other metabolic parameters, suggesting that FGF21 potentially interacts with nonshivering thermogenesis mechanisms to improve insulin sensitivity in these mice." (PMID 40663389, 2025). "Moreover JNK was proposed to induce insulin resistance in obesity via four different mechanisms, including direct inhibition of IRS1 phosphorylation, induction of metabolic inflammation, increased adipogenesis and metabolic efficiency, and negative regulation of the PPARα‐FGF21 axis." (PMID 33038072, 2020).
Insulin resistance (continued). "The absence of increments in insulin resistance parameters despite a sustained peritoneal glucose load suggest that FGF-21 might be an important endocrine agent in PD patients that could possibly act as hormonal signaling to maintain glucose homeostasis and prevent potential insulin resistance." (PMID 26986485, 2016). "However, serum FGF21 levels do not correlate with insulin resistance in the subjects." (PMID 21331285, 2011). "Although markers of insulin resistance (ΔTG/HDL-C ratio, ΔTyG index) as well as liver stiffness and steatosis indices (CAP) showed no significant change after the intervention, plasma FGF21 levels decreased despite stable BMI." (PMID 41228530, 2025). "ALT, alanine aminotransferase; AST, aspartate aminotransferase; FGF21, fibroblast growth factor 21; Gdf15, Growth and differentiation factor 15; HOMA-IR, Homeostatic Model Assessment for Insulin Resistance; NEFA, non-esterified fatty acids." (PMID 36722855, 2023). "Even though FGF21 LKO failed to rescue OVX-induced dyslipidemia, hepatic steatosis, and insulin resistance." (PMID 37834368, 2023). "This nutraceutical combination appears to be safe also in terms of glucose metabolism, since no changes were observed regarding insulin resistance and FGF19 and FGF21 levels." (PMID 30795775, 2019). "We observed that FGF21/sTGFBR2 treatment in control and lipodystrophic LmnaADKO mice housed at thermoneutrality reduced circulating TAG and glucose 4 weeks posttransduction but did not improve insulin resistance in lipodystrophic mice." (PMID 40663389, 2025). "Combined whole body deletion of FGF21 and GDF15 does not result in any additional weight gain in response to high fat feeding but it does result in significantly greater hepatic steatosis and insulin resistance than that seen in GDF15 single knockout mice." (PMID 36064109, 2022). "In addition, it has recently been demonstrated by our group positive correlation between FGF21 and lean body mass and HDL cholesterol in adolescents without insulin resistance, linking the potential effects of FGF21 with glucose metabolism." (PMID 32267352, 2020).
diabetes (364 papers, 2010 to 2026). "Consistent with this, we previously demonstrated that higher FGF21 concentrations predict an increased risk of diabetes." (PMID 40390366, 2025). "FGF21 level was significantly associated with hypertension (p < .001), hypercholesterolaemia (p = .008) and diabetes (p = .008)." (PMID 40356318, 2025). "In the Fenofibrate Intervention and Event Lowering in Diabetes Study including 9697 participants, plasma FGF21 level was significantly associated with cardiovascular outcomes after a 5-year follow-up period." (PMID 40356318, 2025). "Treatment with FGF21 or JPH203 markedly increased levels of EF% and FS% and decreased levels of LVIDs,cardiomyocyte hypertrophy and fibrosis in T1D mice, suggesting that FGF21 can improve diabetes-associated cardiac structure damage and dysfunction." (PMID 39182099, 2024). "Other studies in post-menopausal women with impaired glucose (pre-diabetes) have also shown that FGF21 Levels were independently associated with trabecular bone score (TBS)." (PMID 39341924, 2024). "Further confirmatory studies are needed to fully evaluate the impact of FGF21 production on skeletal metabolism, particularly in high risk populations such as in type 2 Diabetes Mellitus where FGF21 concentrations are higher." (PMID 39341924, 2024). "FGF21 increases with hyperglycemia and predicts the development of diabetes in human studies, and it is also strongly associated with the early stages of nephropathy in T2DM patients." (PMID 39452947, 2024). "Elevated concentrations of FGF-21 have been associated with systemic inflammatory conditions such as Crohn’s disease, diabetes, colitis, sepsis, hyperglycaemia, acute COVID-19, and normo-uricemic gout." (PMID 39330398, 2024). "While increased circulating FGF-21 levels was linked to elevated risk of diabetes, null results were reported in Mendelian Randomization investigations." (PMID 38643166, 2024). "FGF21 levels are associated with obesity and diabetes, and more recently with an increased risk of developing cardiovascular disease (CVD)." (PMID 39519454, 2024). "For further validation of the clinical application of FGF-21 as a risk assessment indicator in the development of diabetes, prospective cohort studies with larger sample sizes are necessary." (PMID 37658393, 2023). "Actually, the administration of recombinant FGF21 would improve the dyslipidemia and weight loss in both animals and clinical diabetes patients." (PMID 37009852, 2023). "Cluster and subgroup analyses were conducted to evaluate the associations between FGF-21 and diabetes in different subpopulations." (PMID 37658393, 2023). "In summary, the present findings further confirm the relationship between high levels of FGF-21 and diabetes, indicating the potential ability of FGF-21 as a biomarker for the risk assessment of diabetes." (PMID 37658393, 2023). "Initially, in the total population, FGF-21 was consistently associated with diabetes after adjustment for confounding factors, including sex, age, BMI, waistline, SBP, and TGs." (PMID 37658393, 2023). "Subsequently, this study demonstrated that FGF-21 was positively related to the risk of diabetes in the total population and subpopulation using restricted cubic splines and multiple logistic regression analyses." (PMID 37658393, 2023). "Higher serum FGF21 levels were inversely associated with the glomerular filtration rate in patients with diabetes." (PMID 37576954, 2023). "In patients with diabetes, high serum levels of FGF21 increase the risk of adverse cardiovascular events during the 5 year follow-up period." (PMID 35369322, 2022). "It has favorable metabolic effects in mice; in humans, however, higher circulating FGF-21 concentrations are associated with dyslipidemia and diabetes." (PMID 35186330, 2022). "Here we conducted a clinical study and an animal experiment to investigate the association between FGF21 and diabetic ED." (PMID 36213282, 2022).
diabetes (continued). "The role of FGF21 in metabolic associated diseases like diabetes mellitus had been confirmed previously." (PMID 36457562, 2022). "Regardless, readily reversible therapies would be desirable given the beneficial effects of FGF21 in ischemic heart disease, especially since those with diabetes are at risk for a coronary event." (PMID 35513431, 2022). "High FGF-21 levels have been also linked to many other metabolic pathologies, such as diabetes mellitus, obesity, or chronic kidney disease." (PMID 34203775, 2021). "Our study sought to measure the serum FGF-21 levels and their associations with lipid profile parameters and oxidative stress in patients with type 2 diabetes mellitus." (PMID 34659937, 2021). "Although high blood sugar and oxidative stress products stimulate FGF21 expression, deficiency of FGF21 enhances germ cell apoptosis due to diabetes -induced oxidative damage." (PMID 34233693, 2021). "Fibroblast growth factor 21 (FGF21) can stimulate bone loss in patients with diabetes and increase in CKD patients." (PMID 34011291, 2021). "As a biomarker, FGF21/adiponectin ratio significantly improved the performance of the traditional risk prediction model for diabetes, with a predictive value that was superior to that of FGF21 or adiponectin alone." (PMID 34321008, 2021). "After excluding participants with diabetes mellitus and quality control, association of single nucleotide polymorphisms (SNPs) with log-transformed FGF21 and FGF23 serum concentrations adjusted for age, sex and principal components of ancestry were analyzed." (PMID 32884031, 2020). "In insulin-deficient mice with diabetes, the authors found that the FGF21 suppressed the secretion of pro-inflammatory cytokines, enhanced retinal antioxidant defense system, restored disorganized cone photoreceptor segments, and improved the retinal function." (PMID 33213461, 2020). "In line with that, fenofibrate treatment significantly ameliorated diabetes-induced renal oxidative stress and dysfunction, and this beneficial effect is associated with increased FGF-21 expression and subsequent activation of NRF-2." (PMID 33317180, 2020). "The diminishing effect on FGF21 level in type 1 and LADA diabetes is probably caused by insulin deficiency, which acts as an inducer of hepatic FGF21." (PMID 30927227, 2019). "Subjects with type 2 diabetes mellitus treated with an engineered FGF21 variant (LY2405319) exhibit clinical improvements, consistent with the attenuation of MCD diet-induced nonalcoholic steatohepatitis in ob/ob mice." (PMID 31570705, 2019). "Patients with diabetes have elevated FGF-21 levels, and plasma FGF-21 has been associated with IR measures including the AUCins in community-dwelling individuals." (PMID 29445355, 2018). "Another issue was associated with the study design which was cross-sectional and did not allow an interpretation on the causal role of high concentrations of FGF21 in diabetes and DR." (PMID 29285020, 2017). "So far, only three prospective cohort studies with relatively small cases numbers (patients with diabetes ranged from 54 to 123) have been conducted, and all reported a positive association between higher FGF-21 levels and increased risk of type 2 diabetes." (PMID 29021814, 2017). "So far, only one prospective study (440 Germans with 54 diabetes cases) has examined the impact of liver enzymes on the association between FGF-21 and diabetes." (PMID 29021814, 2017). "As such, these findings support the diabetes-susceptible NZO mouse as a potential animal model to study endogenous FGF21 actions with regard to the prevention of diabetes." (PMID 28770320, 2017). "After adjustment for risk biomarkers of diabetes including lipids, liver enzymes and inflammatory marker, the OR of type 2 diabetes with per one unit increment in log FGF-21 concentration was 1.16 (95% CI 0.90–1.50)." (PMID 29021814, 2017).
diabetes (continued). "In logistic regression analysis after adjusting for HOMA-IR, insulin, HbA1c and glucose, FGF21 remained significantly associated with diabetes." (PMID 29285020, 2017). "The sex difference in the association between FGF-21 and diabetes risk deserves further investigation and replication in other populations." (PMID 29021814, 2017). "Further researches are needed to validate the findings, to investigate the underlying biological mechanisms, and to examine the feasibility of targeting FGF-21 through pharmacological interventions to reduce the risk of diabetes in high-risk population." (PMID 29021814, 2017). "In conclusion, higher levels of circulating FGF21 were associated with diabetes and various cardiometabolic disease phenotypes." (PMID 25664662, 2015). "Several human studies found that circulation FGF21 levels was positively associated with the degree of hepatic steatosis, type 2 diabetes mellitus (T2DM), and obese." (PMID 26226139, 2015). "In contrast, diagnostic features of diabetes (i.e., higher glucose levels and HbA1c) were associated with higher FGF21 levels." (PMID 25664662, 2015). "A key feature of diabetes is perturbed lipid metabolism, and FGF21 has been implicated in this systemic physiological response as well." (PMID 23981342, 2013). "Deficiency of FGF21 (in FGF21-KO mice) enhanced lipotoxicity and diabetes-induced renal damages, which were significantly prevented by intraperitoneal injection of FGF21." (PMID 24349242, 2013). "Deficiency of FGF21 also further enhanced diabetes-induced oxidative stress and fibrotic effect by upregulation of the expression of renal 3-NT/4HNE and CTGF." (PMID 24349242, 2013). "Oil Red O staining confirmed that deficiency of FGF21 further enhanced diabetes-induced lipid accumulation in the kidney, which was significantly attenuated by administration of FGF21." (PMID 24349242, 2013). "When adjusted for age, gender, BMI, hypertension, diabetes mellitus, log FGF21 was still significantly associated with the presence of LVH (OR per 1-SD increase in log FGF21, 0.422; 95% CI, 0.218 to 0.817; P = 0.010)." (PMID 21525989, 2011). "Higher circulating concentrations of FGF21 have been observed in diabetes mellitus and may be involved in the adverse effects of diabetes mellitus on the skeleton and fracture risk." (PMID 39341924, 2024). "An underlying explanation might be the fact that FGF21 levels are elevated in individuals with subclinical atherosclerosis, diabetes mellitus, and nonalcoholic fatty liver disease." (PMID 39511582, 2024). "Accordingly, our study used a variety of statistical approaches to confirm the current gap in the association of FGF-21 with newly diagnosed type-2 diabetes in the southern China region, providing evidence for the prevention, diagnosis and treatment of diabetes in the clinic." (PMID 37658393, 2023). "It has been proposed that blocking IGFBP1 could prevent bone loss while preserving the insulin-sensitizing benefits of FGF21 therapy in patients with diabetes." (PMID 36967758, 2023). "Likewise, the positive association between FGF-21 and diabetes was also represented in different cluster populations." (PMID 37658393, 2023). "Studies have identified FGF-21 as an independent risk factor for metabolic syndrome and diabetes." (PMID 37658393, 2023). "Therefore, we applied Model 2 (including noninvasive factors and FGF-21) to construct a nomogram, and the model was presented as the nomogram to evaluate the risk of diabetes." (PMID 37658393, 2023). "Finally, this study strengthened the ability of FGF-21 in diabetes risk assessment in the total population and subpopulation with the use of multiple statistical approaches, including multivariate regression analysis, cluster analysis and subgroup analysis." (PMID 37658393, 2023).